EIF6 (eukaryotic translation initiation factor 6)
Diseases named in the same sentence as EIF6 in open-access papers (continued):
Sharing a sentence is not in itself a finding about the gene and the disease.
EIF6 also shares sentences with these, for which no sentence is quoted: gallbladder cancer (2 papers); type 2 diabetes (2); adenocarcinoma (1); aplastic anemia (1); bone marrow failure (1); breast luminal cancers (1); colorectal tumor (1); dyslipidemia (1); head and neck carcinoma (1); hematological cancers (1); intestinal type adenocarcinoma (1); kidney cancer (1); liver cirrhosis (1); lung squamous cell carcinoma (1); lymphoma (1); metastatic colorectal cancer (1); metastatic tumors (1); myelodysplastic syndrome (1); oral squamous cell carcinoma (1); pancreatic adenocarcinoma (1); pancreatic tumor (1); rectum cancer (1); squamous cell carcinoma (1); squamous cell carcinoma of the esophagus (1); T-cell acute lymphoblastic leukaemia (1); T-cell leukemia (1); Treacher-Collins syndrome (1); viral infection (1).